ITPRID2 (ITPR interacting domain containing 2)
Synonyms: CS-1; CS1; KIAA1927; KRAP; SSFA2; SPAG13
Tractability: Antibody: its Gene Ontology location is reachable by antibodies, with high confidence. PROTAC: UniProt records ubiquitination sites on it; ubiquitination databases record sites on it.
Gene: Protein-coding gene on chromosome 2 (181,891,730 to 181,930,738, forward strand). Ensembl gene ENSG00000138434.
Subcellular location: Cytoplasm
Subcellular location (Human Protein Atlas): Cytosol; Plasma membrane; Nucleoplasm
Gene Ontology:
Molecular function: actin filament binding; protein binding; signaling receptor binding
Cellular component: cytosol; plasma membrane; cytoplasm
Genetic constraint (gnomAD): Loss-of-function variants: 53 observed, 104.65 expected, observed/expected ratio (o/e) 0.51, 90% interval 0.41 to 0.64. The upper end of that interval is the gene's LOEUF score, 0.64, which puts it in group 2 of 6, group 1 being the genes least tolerant of losing a copy. Missense variants: 1,459 observed, 1,457.9 expected, observed/expected ratio (o/e) 1, 90% interval 0.96 to 1.04. Synonymous variants: 495 observed, 524.86 expected, observed/expected ratio (o/e) 0.94, 90% interval 0.88 to 1.02.
Homologues: Orthologues: chimpanzee ITPRID2 (99% identical), macaque ITPRID2 (97% identical), rabbit ITPRID2 (87% identical), pig ITPRID2 (87% identical), dog ITPRID2 (86% identical), rat Itprid2 (82% identical), mouse Itprid2 (82% identical), guinea pig ITPRID2 (78% identical), tropical clawed frog itprid2 (52% identical), zebrafish itprid2 (28% identical). Paralogues in human: ITPRID1 (17% identical), TESPA1 (10% identical).
Diseases named in the same sentence as ITPRID2 in open-access papers:
ITPRID2 is named in the same sentence as 14 diseases in open-access papers, as found by Europe PMC text mining. Sharing a sentence is not in itself a finding about the gene and the disease. The quoted sentences say what the papers report.
colon cancer (2 papers, 2021 to 2023). "KRas-induced actin-interacting protein (KRAP), now designated IP3 receptor-interacting domain-containing protein 2 (ITPRID 2), was originally identified as a large actin-binding protein that is over-expressed in a colon cancer cell line expressing activated KRas33." (PMID 34301929, 2021).
tumor (4 papers, 2014 to 2022). "QRT-PCR showed that the expression of the DRAXIN, ITPRID2, and MAP3K1 were significantly upregulated while MOXD1 was downregulated in tumor samples." (PMID 36045691, 2022).
ITPRID2 also shares sentences with these, for which no sentence is quoted: cancer (6 papers); prostate carcinoma (4); colorectal cancer (3); glioma (3); Globozoospermia (1); Hypoinsulinemia (1); Insulin resistance (1); lung carcinoma (1); male infertility (1); mastitis (1); Obesity (1); oral squamous cell carcinoma (1).